TVP23C (trans-golgi network vesicle protein 23 homolog C)
Synonyms: FAM18B2; MGC8763
Tractability: Antibody: UniProt predicts a signal peptide or a membrane-spanning region. PROTAC: ubiquitination databases record sites on it.
Gene: Protein-coding gene on chromosome 17 (15,502,264 to 15,563,595, reverse strand). Ensembl gene ENSG00000175106.
Subcellular location: Membrane
Subcellular location (Human Protein Atlas): Golgi apparatus
Gene Ontology:
Biological process: vesicle-mediated transport
Cellular component: Golgi apparatus; Golgi membrane; membrane
Genetic constraint (gnomAD): Loss-of-function variants: 19 observed, 27.15 expected, observed/expected ratio (o/e) 0.7, 90% interval 0.49 to 1.03. The upper end of that interval is the gene's LOEUF score, 1.03, which puts it in group 4 of 6, group 1 being the genes least tolerant of losing a copy. Missense variants: 185 observed, 235.14 expected, observed/expected ratio (o/e) 0.79, 90% interval 0.7 to 0.89. Synonymous variants: 68 observed, 82.66 expected, observed/expected ratio (o/e) 0.82, 90% interval 0.68 to 1.01.
Homologues: Orthologues: chimpanzee TVP23C (93% identical), dog TVP23B (90% identical), rabbit TVP23C (90% identical), mouse Tvp23b (89% identical), rat Tvp23b (86% identical), guinea pig Tvp23c (86% identical), rat AABR07006081.1 (82% identical), macaque TVP23B (76% identical), zebrafish tvp23b (70% identical), zebrafish zgc:112148 (62% identical), Drosophila melanogaster CG5021 (45% identical), Caenorhabditis elegans C34D4.4 (34% identical). Paralogues in human: TVP23B (96% identical), TVP23A (54% identical).
Diseases named in the same sentence as TVP23C in open-access papers:
TVP23C is named in the same sentence as 2 diseases in open-access papers, as found by Europe PMC text mining. Sharing a sentence is not in itself a finding about the gene and the disease. The quoted sentences say what the papers report.
triple-negative breast carcinoma (1 paper, 2024). An invasive breast carcinoma which is negative for expression of estrogen receptor (ER), progesterone receptor (PR), and human epidermal growth factor receptor 2 (HER2). "Notably, the TRs of several genes, including SYNGR1, GTF2IRD2, and FAM120C, exhibited increased levels in the tumor samples of triple-negative breast cancer patients, whereas genes such as TVP23C, ICAM3, and RIMKLB displayed decreased TRs in triple-negative breast cancer tumor samples." (PMID 39349823, 2024).
TVP23C also shares sentences with these, for which no sentence is quoted: tumor (1 paper).